CD4 (CD4 molecule)
Diseases named in the same sentence as CD4 in open-access papers (continued):
Sharing a sentence is not in itself a finding about the gene and the disease.
colitis (continued). "Consequently, Ddx21-deficient CD4+ T cells exhibit resistance to inducing adoptive transfer colitis, with recipients showing reduced T cell infiltration compared to wild-type (WT) counterparts." (PMID 42210780, 2026). "CD4+ Treg demonstrated pronounced enrichment of energy metabolism-associated gene signatures, a finding corroborated by elevated mitochondrial complex gene signature scores indicating heightened activation in the colitis model." (PMID 41356191, 2026). "Here, we show that overexpressing Prdm1 down-regulated IL-2 signaling, whereas Prdm1-deficiency enhanced IL-2 signaling in mouse CD4+ T cells and Treg cells with augmented IL-2 signaling in T cells from influenza-infected mice and during adoptive T cell transfer–induced colitis." (PMID 40680114, 2025). "Moreover, Etv1 deficiency attenuates CD45RBhighCD4+ T cell-induced colitis, characterized by a reduction in pathogenic CD4+ T cells in the intestinal mucosa." (PMID 41347630, 2025). "Experimental colitis studies explored the pathogenic mechanism of CD4+T cell-derived IL-9 in IBD." (PMID 40099014, 2025). "First, to address whether PRR deficiency enhances the proliferation and pathogenicity of Th1 and Th17 cells in colitis, we transferred naive CD4 T cells from PRRcKO mice into RAG2-deficient mice." (PMID 41451235, 2025). "Furthermore, this cytokine elevation promotes the transformation of CD4+ T cells into pathogenic T cells that produce granulocyte-macrophage colony-stimulating factor in vivo, thus promoting the development of colitis and colorectal cancer." (PMID 41515203, 2025). "Meanwhile, Hobit and Blimp-1, which plays crucial role in CD8+ TRM cell generation, have been shown to be dispensable for CD4+ TRM cell formation in the colon during experimental colitis, although their deficiency impairs the expression of pro-inflammatory cytokines in CD4+ TRM cells." (PMID 40391228, 2025). "Our results demonstrate that IL-36γ stimulation of naive CD4+ T cells significantly induced IFNγ expression in vitro and was associated with augmented intestinal inflammation in vivo using the T cell transfer model of colitis." (PMID 40642091, 2025). "High expression of Smad7 in CD4+ T cells is associated with severe colitis." (PMID 39185411, 2024). "For example, the adoptive transfer of CD69-deficient CD4+ T cells into RAG-/- mice (deficient in lymphocytes) induced severe colitis due to the increased secretion of proinflammatory cytokines (IFN-γ, TNF-α, IL-21) and decreased levels of anti-inflammatory cytokines (TGF-β1)." (PMID 39451246, 2024). "In addition, CD4+ T cell differentiation profiles often associated with the improvement in DSS-induced colitis." (PMID 38500062, 2024). "In DSS-induced colitis mice (6–8 weeks), iron deficiency promoted colonic CD4+ T cell infiltration." (PMID 39127747, 2024). "Since the reduced colitis severity was associated with a shift of CD4+ T-cell infiltration towards Foxp3+ Treg cells, we hypothesised that Foxp3+ Treg cells contribute to the limitation of colonic inflammation." (PMID 38839272, 2024). "Altogether, these analyses suggest that only the five identified master gene regulators associated with the colitis inflammatory condition could be responsible for the altered phenotype observed in colonic CD4+ T cells." (PMID 38719901, 2024). "Importantly, these mice develop severe intestinal inflammation and colitis, and this is linked to increased histone acetylation marks in all TH subsets of CD4-Cre;Odcfl/fl mice and in select TH subsets of CD4-Cre;Dohhfl/fl mice." (PMID 39125743, 2024). "Moreover, the infusions of Tfam-deficient Tregs functionally fail to resolve the accumulation of pathogenic CD4+ effector T cells in the adoptive T cell transfer colitis model and accordingly advance disease severity." (PMID 37809060, 2023). "Moreover, Rpa1fl/fl Cd4‐cre mice exhibit increased susceptibility to inflammatory diseases, including colitis and hepatitis." (PMID 36721037, 2023).
colitis (continued). "Indeed, the in vivo suppression assay using immune-deficient Rag1−/− mice clearly showed that very severe colitis, induced by injection of naive CD4+-T cells, cannot be inhibited by Ube2m-deficient Treg cells." (PMID 35641500, 2022). "While the transfer of Ihh HET CD4+ T cells potently induced colitis, transfer of Ihh KO CD4+ T cells showed strongly diminished colitis indicated by reduced weight loss, reduced colon thickening/shortening and reduced mucosal infiltration of T cells expressing IL-17a, IL-22 and IFNγ in the colon." (PMID 35835905, 2022). "In addition, IRF5 in CD4+ T cells promotes Th1 and Th17 associated cytokines, decreases Th2 associated cytokines and enhances the severity of experimental colitis in mice." (PMID 35967345, 2022). "was one of the first groups to show that transfer of CD4+CD25+ Tregs could successfully treat colitis in immune deficient mice within two weeks of infusion." (PMID 36466912, 2022). "Because of the increased expression in colonic T cells from patients with IBD, we tested the effect of GPR183 deficiency in the T cell transfer model of colitis, in which CD4+ CD45RBhigh (naïve) T cells, depleted of regulatory T cells, are adoptively transferred into Rag1-/- recipients." (PMID 36389671, 2022). "Here, our data uncover a pathogenic role of CD69+CD103− CD4+ TRM cells in DSS-induced colitis." (PMID 35844584, 2022). "To test whether CD4 T cells were similarly affected by Arl4d deficiency, we used the model of transfer colitis by the adoptive transfer of CD25negCD62Lhigh CD4 T cells from either Arl4d+/+ or Arl4d−/− mice into Rag2-deficient mice." (PMID 36078047, 2022). "Furthermore, the change in the numbers of different subpopulations of CD4+ mTfh cells in colitis mice is associated with SSP treatment." (PMID 35388299, 2022). "We also demonstrated that inhibition of IL-12/IL-23-mediated signaling, using anti-p40 antibodies, was sufficient to attenuate colitis severity in TAGAP-deficient mice, suggesting that colitogenic CD4+ T cells critically mediate the severe colitis phenotype seen in TAGAP deficiency." (PMID 36704549, 2022). "A decreased CD4+ T-cell population was restored after administration of 8-Br-cGMP, suggesting that Npr1 deficiency shifted T-cell population in the process of colitis." (PMID 35794311, 2022). "Our data confirmed that the numbers of both CD69+CD103− and CD69+CD103+ CD4+ TRM cells were significantly increased in the colon of DSS-induced colitis, which was associated with more severe disease activities, pointing to the critical role of TRM cells in the development of colitis." (PMID 35844584, 2022). "Moreover, iNKT cells contribute to protection against IFNγ-mediated colitis by limiting an increase in pathogenic CD25+CD4+ effector T cells." (PMID 36499642, 2022). "We explored whether CD4+ T cells were important mediators of the severe colitis phenotype observed in TAGAP deficiency." (PMID 36704549, 2022). "Furthermore, loss of VDR signaling in lymphocytes resulted in the generation of pathogenic CD8+ T cells and development of IBD and CD4+ T cells from VDR knock-out (KO) mice induced more severe colitis than wild-type CD4+ T cells." (PMID 36341397, 2022). "In addition, epithelial PBLD deficiency in TNBS-induced colitis was associated with decreased CD4+ Foxp3+ cells (a marker of T regulatory cells) and increased IL-17A+ cells." (PMID 34059646, 2021). "Furthermore, Th17 differentiation and plasticity towards Th1-like cells was increased in vivo in a T-cell intrinsic way, and Tec-deficient naïve CD4+ T cells differentiated more into Th1/exTh17 cells in a colitis model, leading to a stronger disease outcome." (PMID 35003062, 2021). "However, the D5R deficiency and CCR9 deficiency in CD4+ T-cells reduced the development of colitis in a similar manner." (PMID 34884737, 2021). "Thus, a D5R deficiency in CD4+ T-cells limits the development of experimental colitis and impairs its migration into the gut mucosa." (PMID 34884737, 2021).
colitis (continued). "In this study, we found that Themis-deficient CD4+ T cells had poor proliferative responses, reduced cytokine production in vitro and weaker inflammatory potential, as measured by their ability to cause colitis in vivo." (PMID 33177694, 2021). "Susceptibility to colonic inflammation has previously been shown to increase following stress due to sensitization of CD4(+) lymphocytes, with the increased susceptibility able to be transferred to other rats with intravenous transfer of the CD4(+) lymphocytes." (PMID 33807290, 2021). "Rag–/– mice receiving D5R-deficient naïve CD4+ T-cells manifested less severe colitis in comparison with mice receiving D5R-sufficient naïve CD4+ T-cells, and their body weight increased with the time course of the experiment, similar to the expected body weight increase with age in healthy mice." (PMID 34884737, 2021). "In contrast, upon adoptive transfer and induction of colitis the subset distribution of NCOR1-deficient CD4+ T cells is changed and hence the percentage of IFNγ+ Th cells might be reduced." (PMID 32318068, 2020). "Notably, a recent study showed that the effect of colitis-associated inflammation on CD4 T cells affects the severity and mortality of Clostridium difficile infections." (PMID 32670220, 2020). "Co-transfer of transfer of IL-9 secreting T-cells with CD45RBhi CD4+ T-cells aggravates transfer colitis in recombination-activating gene 1-deficient mice and anti-IL-9 antibodies can be used to treat established oxazolone colitis." (PMID 31906479, 2020). "However, our data showed different expression patterns of CXCR3 and PD-1 on the pathogenic T cell subsets for colitis and cholangitis, the colon CD4+ T cells and the hepatic CD8+ T cells, respectively." (PMID 29868034, 2018). "We next sought to examine whether the intestinal microbiota contributes to the exacerbated colitis caused by the expanded IFNγ-producing CD4+ T-cell population in Cnb1CD4 mice." (PMID 29515579, 2018). "Furthermore, SMAD2-deficient CD4 T cells were unable to initiate colitis in a RAG adoptive transfer model and in a C. rodentium model of infectious colitis." (PMID 29910812, 2018). "Macrophage-specific deletion of WASP causes severe colitis in a naive CD4+ T-cell transfer model." (PMID 29725003, 2018). "IL-27 might mediate this effect by inhibiting cell death, similar to what has been shown in a colitis model and as we reported for CD4 T cells deficient in the IL-27 co-receptor gp130 during chronic LCMV infection." (PMID 30044874, 2018). "As we observed the relevance of IFN-γ and the role of CD4+ T cells for CS-induced inflammation above, we exposed T-bet-deficient mice to CS for 4 weeks to assess the role of the Th1 response in CS exposure-induced colitis and lung inflammation." (PMID 29163466, 2017). "In addition, CD4+ T cells with high expression of CD45RB are able to induce pathogenic TH1 responses that lead to colitis." (PMID 28361039, 2017). "To determine whether CerS6 splenocytes differed in their ability to induce colitis, we isolated naïve CD4+CD45RBhi cells from either wild type or CerS6-deficient mice and adoptively transferred them into RAG1-deficient recipients." (PMID 29138469, 2017). "Next, we examined whether SHP2-deficiency in CD4+ T cells impacts the colitis progression using DSS-induced colitis model." (PMID 27935860, 2017). "Here, we investigated whether the regulatory CD4+ NKG2D+ T cells are associated with colitis induced by dextran sodium sulphate (DSS) in mice." (PMID 28224733, 2017). "Furthermore, another study demonstrated that adoptive transfer of IL-17A deficient naıve CD4+ T cells or transfer of IL-17 receptor deficient T cells to immuno-deficient recipients provokes severe colitis." (PMID 28584821, 2017). "To assess whether JunB is also required for other TH17-mediated diseases, we investigated the function of JunB in colitis development by transferring Junb-deficient CD4+CD45RBhiCD25− T cells into Rag1-deficient mice." (PMID 28555647, 2017).
colitis (continued). "Indeed, CD4 CTLs are critically involved in the induction of colitis since colitis induction is reduced in granzyme B-deficient mice." (PMID 28280496, 2017). "Intragastric administration of κ-carrageenan to BALB/c mice prior to the induction of oxazolone colitis resulted in an aggravation of body weight loss, a decrease in the survival ratio, aggravation of colonic inflammation, and decrease in the ratio of CD4 + CD25+/CD4+." (PMID 27015810, 2016). "Therefore, in addition to their impaired capacity to expand in the lymphopenic environment, reduced production of this Th1 cytokine also contributed to the reduced capacity of TNFR2-deficient naïve CD4 cells to induce colitis in lymphopenic mice." (PMID 27601345, 2016). "In conjunction with the persistent impaired proliferative expansion of TNFR2 deficient CD4 T cells in vivo, TNFR2 should contribute at least in part to the in vivo differentiation of pathogenic Th1 cells in mouse colitis induced by transfer of naive CD4 T cells." (PMID 27601345, 2016). "In addition, the concentration of pro-inflammatory cytokines, in particular IFN-γ, TNF-α and IL-6 secreted by total LP cells in the colon, was two- to sixfold higher in IL-15-deficient mice with CD4+ T-cell-driven colitis compared with RAG2ko host mice." (PMID 26964669, 2016). "Importantly, the loss of Foxo expression in Gimap5sph/sph CD4+ T cells correlated with a loss of Treg population and function and likely represents an important determinant of the colitis pathology observed in these mice." (PMID 25944983, 2015). "Since both Th1 and Th17 cells are associated with colitis, we investigated whether Tpl2 altered the proportions of IFNγ or IL-17A positive CD4 T cells within the spleen and mesenteric lymph nodes (MLN)." (PMID 25781948, 2015). "In the present study oral administration of hyperimmune colostrum preparations enriched with anti LPS effectively alleviated immune mediated colitis in mice and was associated with a significant induction of CD4 + CD25+ and CD4 + Foxp3+ regulatory T cells in the spleens of treated mice." (PMID 26518263, 2015). "Here, we show that brain mAChR mediated cholinergic activation results in a decreased susceptibility to experimental colitis; this effect is vagus nerve- and splenic nerve-dependent and mediated at a cellular level by a specific interaction between CD11c+ DCs and CD4+/CD25− T cells." (PMID 25295619, 2014). "This was accompanied by a reduced activation of NFκB, in β5i/LMP7-deficient cells and reduced Th1 and Th17 but enhanced Treg cell differentiation of CD4+ T-cells in the lamina propria of β5i LMP7-deficient/inhibitor-treated mice with mild forms of DSS-induced colitis." (PMID 24740379, 2014). "Finally, to test if the ablation of PP4 enhanced the overall colitogenic ability of peripheral T cells, we adoptively transferred WT or PP4-deficient CD4+CD45RBhi cells into RAG1-/- recipients to induce experimental colitis." (PMID 24904742, 2014). "Lastly, to test whether the functional defect in CD4cre:PP4f/f Treg cells was the predominant cause for the spontaneous colitis in the CD4cre:PP4f/f mice, we co-transferred WT or CD4cre:PP4f/f Treg cells with WT CD4+CD45RBhigh T cells into RAG1-/- recipients." (PMID 24904742, 2014). "Furthermore, analogous to the CD4 T cell-induced colitis, TREM-1 deficiency resulted in reduced colonic mRNA expression of several pro-inflammatory mediators." (PMID 24453980, 2014). "Additionally, support for the involvement of TRPV1 in chronic colitis comes from animal studies of TNBS colitis, dextran sulfate-induced colitis, and colitis caused by adoptive transfer of CD4+/CD25− T cells in SCID mice." (PMID 25045574, 2014). "We report here that the abrogation of inducible MHCII expression on IECs during chronic H. hepaticus infection and anti-IL-10R mAb treatment leads to overt colitis associated with an augmented accumulation of CD4+ Th1 cells and an increased CD4+ T cell:FoxP3+ Treg cell ratio." (PMID 24489792, 2014).
colitis (continued). "β5i/LMP7-deficient mice are resistant to development of DSS-induced colitis, due to reduced NFκB activation or to altered CD4+ T-cell differentiation, which both may dampen the production of (pro)inflammatory cytokines." (PMID 24740379, 2014). "To examine whether IFN-γ is responsible for inducing epithelial MHCII expression we made use of the adoptive transfer colitis model in which lymphocyte-deficient mice develop colitis upon transfer of CD4+ CD45RBhi T cells." (PMID 24489792, 2014). "The idea that T cells must be tolerized to commensal microbiota was suggested decades ago, when in an adoptive transfer model, naïve CD4 T cells caused colitis but were held in check by another population of CD4 T cells, now known as regulatory T cells (Tregs)." (PMID 25120539, 2014). "Only when we adoptively transferred TR2-deficient cells into a completely lymphopenic environment (RAG-1 deficiency), strong colitis developed within 30 d (E and unpublished data), which was accompanied by a massive infiltration of CD4+ T cells to mesenteric lymph nodes." (PMID 24115907, 2013). "Interestingly, CD4+CD45RBhi adoptive transfer into CA-MLCKRAG1−/− mice causes a much more severe colitis, with an earlier onset, compared to transfer into RAG−/− mice." (PMID 24062746, 2013). "In addition, co-transfer of Nod2 deficient activated/memory CD4+CD45RBlow T cells prevented the induction of colitis and induced a development of Foxp3+ Treg cells comparable to the one observed after transfer of wild type T cells." (PMID 24324812, 2013). "However, in the CD45RBhigh T-cell-transfer colitis model, we show that CXCR6-deficient CD4+ T cells retain the ability to induce wasting and colitis." (PMID 23840334, 2013). "In addition, cooperation between iTreg and nTreg cells appears to be required for protection from the autoimmune disease that develops in Foxp3-deficient mice 133, and protection from colitis induced by transfer of naive CD4+ T cells." (PMID 23405904, 2013). "However, in the models we have previously used for experimental DSS inducing epithelial injury (i.e., leaky mucosa) resulting in colitis or pathogenic CD4+CD45RBhigh T cell transfer; IFNγ seems to be involved in the pathogenesis of the induced colitis." (PMID 22423982, 2012). "In TCRα−/− mice and T-cell-transfer-induced colitis, high expression of IL-7Rα on T cells is associated with colitis, and IL-7-producing bone marrow cells may harbor colitogenic memory CD4+ T cells." (PMID 23057802, 2012). "Indeed, it was shown that adoptive transfer of IL-17A-deficient naïve CD4+ T cells to recipient immunodeficient mice results in severe colitis." (PMID 22082127, 2011). "We examined whether a defect in CD4+FoxP3+ regulatory T cells (Treg) underpins the pathogenesis of colitis in the Gαi2−/− (Gαi2-deficient) colitis model." (PMID 21966415, 2011). "Finally, reduced co-stimulation in either B7.1 or B7.2-deficient recipients resulted in a dramatic acceleration of colitis induction following transfer of CD4+CD45RBhigh cells." (PMID 19333372, 2009). "In addition, N297A was shown to have therapeutic activity in a murine colitis model induced by adoptive transfer of IL-10 deficient CD4+ T cells." (PMID 19172487, 2009). "Using a T-cell transfer model of colitis we found that CD4+ CD25+ TR cells from Gpr83-deficient mice were able to suppress the development of colitis induced by wild-type or Gpr83−/− CD45RBhi naïve CD4+ T cells." (PMID 18479351, 2008). "Similarly, anti-IL-17 treatment had little impact on the T cell-mediated colitis that develops in IL-10-deficient mice or in RAG-deficient recipients of IL-10-deficient CD4+ T cells, although the colitis was dependant on IL-23." (PMID 18400195, 2008). "Thus Gpr83-deficient mice had normal frequencies of CD4+ Foxp3+ cells in the primary and secondary lymphoid organs and these cells retained their suppressive activity in vivo in a T-cell transfer model of colitis." (PMID 18479351, 2008).